TBC1D3 (TBC1 domain family member 3)
Description:
Acts as a GTPase activating protein for RAB5. Does not act on RAB4 or RAB11.
Synonyms: PRC17; TBC1D3A; DKFZp434P2235
Tractability: Antibody: UniProt places it where antibodies can reach, with high confidence; its Gene Ontology location is reachable by antibodies, with medium confidence. PROTAC: UniProt records ubiquitination sites on it; ubiquitination databases record sites on it.
Gene: Protein-coding gene on chromosome 17 (38,181,659 to 38,194,017, reverse strand). Ensembl gene ENSG00000274611.
Subcellular location: Cell membrane
Subcellular location (Human Protein Atlas): Vesicles
Pathways (Reactome):
Vesicle-mediated transport: TBC/RABGAPs
Gene Ontology:
Molecular function: GTPase activator activity
Biological process: regulation of cilium assembly
Cellular component: early endosome membrane; endosome; membrane; plasma membrane
Homologues: Orthologues: chimpanzee TBC1D3B (97% identical). Paralogues in human: TBC1D3C (100% identical), TBC1D3D (99% identical), TBC1D3E (99% identical), TBC1D3F (99% identical), TBC1D3I (99% identical), TBC1D3K (99% identical), TBC1D3H (99% identical), TBC1D3L (99% identical), TBC1D3G (99% identical), TBC1D3B (99% identical), TBC1D26 (30% identical), USP6NL (29% identical), and 33 more.
Diseases named in the same sentence as TBC1D3 in open-access papers:
TBC1D3 is named in the same sentence as 26 diseases in open-access papers, as found by Europe PMC text mining. Sharing a sentence is not in itself a finding about the gene and the disease. The quoted sentences say what the papers report.
breast carcinoma (8 papers, 2017 to 2025). "However, we cannot exclude the possibility that EMT is also involved in the TBC1D3-induced cell migration, because there is evidence that loss of E-cadherin is not a necessity for epithelial to mesenchymal transition in human breast cancer." (PMID 28422741, 2017). "Previous studies showed that TBC1D3 upregulated tumor necrosis factor-α (TNF-α)-induced breast cancer cell migration." (PMID 34553038, 2021). "For example, TBC1D3 is observed to be overexpressed in breast cancer by promoting oxidized low-density lipoprotein receptor 1 expression required for cell migration involving in TNFα/NF-κB signaling." (PMID 33194704, 2020). "Taken together, these results suggest that CaM interacts with TBC1D3 and inhibits GF signaling-induced ubiquitination at K166 and subsequent degradation of the oncoprotein in human breast cancer cells." (PMID 28422741, 2017). "Recently, TBC1D3 was shown to enhance GF signaling, which plays a critical role in metastasis of breast cancer cells to other organs." (PMID 28422741, 2017). "Together, these data indicate that TBC1D3 promotes the migration of human breast cancer cells in a manner involving the expression and activation of MMP-9." (PMID 28422741, 2017). "Taken together, these data indicate that CaM enhances the TBC1D3-induced migration of human breast cancer cells by a mechanism involving the expression and activation of MMP-9." (PMID 28422741, 2017). "We next sought to examine the mechanism by which CaM inhibits the GF-induced degradation of TBC1D3 in human breast cancer cells." (PMID 28422741, 2017). "Together, these data indicate that CaM expression enhances the TBC1D3-induced migration of human breast cancer cells." (PMID 28422741, 2017). "Recently, TBC1D3 was found to promote breast cancer cell migration." (PMID 34553038, 2021). "Finally, it was shown that TBC1D3 affects the migration of human breast cancer cells by regulating TNFα/NF-κB signaling." (PMID 31529038, 2019). "We next asked whether endogenous CaM protects TBC1D3 from GF-induced degradation in human breast cancer cells." (PMID 28422741, 2017). "CaM specifically interacts with TBC1D3 in a Ca2+-dependent manner and inhibits GF signaling-induced ubiquitination and degradation of the oncoprotein in both cytoplasm and the nucleus of human breast cancer cells." (PMID 28422741, 2017). "In the present study, we demonstrate that CaM specifically interacts with TBC1D3 in a Ca2+-dependent manner and inhibits GF signaling-induced ubiquitination and degradation of the oncoprotein in both cytoplasm and the nucleus of human breast cancer cells." (PMID 28422741, 2017). "Finally, we find that TBC1D3 promotes the expression and activation of MMP-9 and the migration of human breast cancer cells, and interaction with CaM considerably enhances such effect of TBC1D3." (PMID 28422741, 2017). "However, it was unknown whether TBC1D3 had any effect on the migration and metastasis of breast cancers." (PMID 28422741, 2017). "TBC1D3 was first described as an oncogene and was also identified as PRC17 during the analysis of cells derived from prostate and breast cancer patients." (PMID 31529038, 2019). "Recently, TBC1D3 was showed to enhance GF signaling, which has also been shown to stimulate the expression of MMP-9 at the transcriptional level in breast cancer cells." (PMID 28422741, 2017). "However, CaM overexpression drastically reduced the FCS-induced ubiquitination of TBC1D3, further supporting a role for CaM in suppressing the FCS-induced degradation of TBC1D3 in human breast cancer cells." (PMID 28422741, 2017).
prostate carcinoma (3 papers, 2012 to 2020). A carcinoma that arises from epithelial cells of the prostate gland. "TBC1D3C is a member of the TBC1D3 gene family, which has been linked to prostate cancer and tumour formation in mice." (PMID 26335491, 2015). "TBC1D3 (also referred to as PRC17) is overexpressed in prostate cancer and its overexpression promotes the growth of NIH3T3 cells." (PMID 33194704, 2020). "TBC1D3 is a hominoid specific gene previously identified as an oncogene in breast and prostate cancers." (PMID 22348058, 2012).
heart failure (2 papers, 2023 to 2024). Inability of the heart to pump blood at an adequate rate to meet tissue metabolic requirements. "In contrast, by using gene features, our posterior distribution of shet indicates that PLN is strongly constrained, but TBC1D3 is not, consistent with the observation that heterozygous LOFs in PLN cause severe cardiac dilation and heart failure." (PMID 37292653, 2024). "In contrast, by using gene features, our posterior distributions of shet indicate that PLN is strongly constrained but TBC1D3 is not, consistent with the observation that heterozygous LOFs in PLN cause severe cardiac dilation and heart failure." (PMID 37398424, 2023).
hepatocellular carcinoma (2 papers, 2012 to 2024). A malignant tumor that arises from hepatocytes. "To determine whether TBC1D3 modulates signal transduction through the insulin receptor, we examined insulin signaling in HepG2 cells (American Type Culture Collection, Manassas, VA), a well-studied human hepatocellular carcinoma cell line." (PMID 22348058, 2012). "The results showed that the decrease of STC1 expression promoted the expression of TBC1 domain family member 3 (TBC1D3), led to the decrease of STAT phosphorylation level, and further inhibited the proliferation and migration of hepatocellular carcinoma in vitro." (PMID 39654892, 2024).
asthma (1 paper, 2023). "We screened seven candidate diagnostic biomarkers for asthma using LASSO regression (namely, BCL10, CD300E, IER2, MMP13, OAF, TBC1D3, and TMEM151A), among which the area under the curve (AUC) value for CD300E and IER2 were 0.722 and 0.856, respectively." (PMID 37259023, 2023).
clear cell renal cell carcinoma (1 paper, 2021). "In addition, TBC1D3D may positively regulate proliferation, and overexpression of TBC1D3 promoted clear cell renal cell carcinoma proliferation in vitro." (PMID 34553038, 2021).
idiopathic intracranial hypertension (1 paper, 2024). "We found a significant difference between the two groups, in which genes such as CLEC2A, TBC1D3, and DPP10 were upregulated in the group of idiopathic intracranial hypertension." (PMID 39605979, 2024).
lung adenocarcinoma (1 paper, 2021). A carcinoma that arises from the lung and is characterized by the presence of malignant glandular epithelial cells. "The results showed that the TBC1D3 expression was respectively higher in KIRC, KIRP (kidney renal papillary cell carcinoma), LIHC (liver hepatocellular), LUAD (lung adenocarcinoma), LUSC (lung squamous cell carcinoma), and THCA (thyroid carcinoma)." (PMID 34553038, 2021).
metastatic prostate carcinoma (1 paper, 2024). A carcinoma that arises from the prostate gland and has spread to other anatomic sites. "TBC1D3 was a GAP for Rab5, which was up-regulated in metastatic prostate cancer." (PMID 39439452, 2024).
tumor (10 papers, 2012 to 2024). "TBC1D3 is overexpressed or mutated in a variety of human cancers, implying its involvement in tumor development and/or progression." (PMID 23029530, 2012). "Moreover, exogenously expressed TBC1D3 is able to transform mouse cells and induce tumor formation in nude mice, suggesting a causative link between TBC1D3 expression and tumorigenesis." (PMID 23029530, 2012). "UALCAN showed that five TBC1D3 members had higher expression levels in KIRC tumor tissue compared to normal tissue." (PMID 34553038, 2021). "Our laboratory has focused on the regulation of TBC1D3 degradation as well as its role in tumor development and progression." (PMID 28422741, 2017). "The precise biological function of TBC1D3 and the role it plays in tumor development and progression are still under investigation." (PMID 23029530, 2012). "The tumor cells migration might be induced by TBC1D3, therefore an inhibition of NF-κB could result in the migration suppression thanks to CAPE addition." (PMID 29048370, 2017). "Furthermore, the role of TBC1D3 in aggressive tumor behavior remains completely undefined." (PMID 28422741, 2017). "Results show that leptin signaling increases the expression of tumor progression and chemoresistance-related genes (ABCB1, WNT4, ADHFE1, TBC1D3, LL22NC03, RDH5, ITGB3) in TNBC cells." (PMID 32471192, 2020). "Since MMP-9 can promote the migration and metastasis of tumor cells through degradation of extracellular matrix (ECM) components, we next examined the effect of TBC1D3 on the expression and activation of this endopeptidase in MCF-7 cells." (PMID 28422741, 2017).
cancer (6 papers, 2012 to 2024). A tumor composed of atypical neoplastic, often pleomorphic cells that invade other tissues. "TBC1 domain family member 3 (TBC1D3) is a plasma membrane protein overexpressed in several human cancers." (PMID 33981723, 2021). "COL27A1, PRUNE2, MAEA, TBC1D3, GADD45B, ANXA8 and TSPY1 have been confirmed to play a pro‐resistant role in various cancers, which reflects the reliability of the hGeCKO library screening to some extent." (PMID 39550701, 2024).
TBC1D3 also shares sentences with these, for which no sentence is quoted: biliary tract cancer (1 paper); bone neoplasm (1); breast tumors (1); colorectal cancer (1); dilation (1); gall bladder cancer (1); glaucoma (1); intellectual impairment (1); lung squamous cell carcinoma (1); malaria (1); microphthalmia (1); prostate tumors (1); renal cysts and diabetes syndrome (1); skin cutaneous melanoma (1); thyroid carcinoma (1).